HDAC3 (histone deacetylase 3)
Diseases named in the same sentence as HDAC3 in open-access papers (continued):
Sharing a sentence is not in itself a finding about the gene and the disease.
colitis (10 papers, 2021 to 2025). Inflammation of the colon. "Specific deletion of Hdac3 in the gut of mice fed a high‐fat diet has been observed to enhance susceptibility to colitis, highlighting the critical role HDAC3 plays in inflammation‐related digestive diseases." (PMID 39143689, 2025). "In colitis, histone deacetylase 3 (HDAC3) regulates the GBP5-NLRP3 axis in macrophages, alleviating inflammation and disease severity." (PMID 40788157, 2025). "To clarify the mechanism of HDAC3 in CX3CR1-positive monocytes in DSS-induced colitis, we then performed RNA sequencing to analyze the gene expression profiles in the colonic mucosa." (PMID 38903915, 2024). "Conditional knockout (cKO) of Hdac3 in CX3CR1 positive cells attenuated the disease severity of Dextran Sulfate Sodium (DSS)-induced colitis." (PMID 38903915, 2024). "Lastly, conditional knockout of Hdac3 in macrophages (Hdac3 mKO) attenuated the disease severity of DSS-induced colitis." (PMID 38903915, 2024). "Mechanically, the current study revealed that HDAC3 promotes the development of colitis in macrophages by positively regulating IFN-γ-induced expression of GBP5 and enhancing the activation of NLRP3 inflammasomes in GBP5-dependent manners." (PMID 38903915, 2024). "The results displayed that the bodyweights of WT mice were significantly decreased from 4 days post administration of DSS, and conditional knockout of HDAC3 ameliorated the bodyweight decrease levels during DSS-induced colitis." (PMID 38903915, 2024). "Loss of HDAC3 in CX3CR1 positive monocytes or macrophages attenuated the activation of inflammasomes and tissue damage in mouse colitis." (PMID 38903915, 2024). "Further, epithelium-intrinsic ablation of HDAC3 decreased commensal-specific Tregs, increased commensal-specific Th17 cells, and promoted T cell–driven colitis." (PMID 36602872, 2023). "A recent study demonstrated that IP3 can increase HDAC3 activity in the epithelium to promote tissue repair in DSS-induced colitis mice." (PMID 36794012, 2023). "Our study showed that MLT mediated butyrate-improved SD-induced colitis through the MCT1/HDAC3/P-GSK-3β/HIF-1α/NF-KB loop." (PMID 34769321, 2021). "In conclusion, inhibition of HDAC3 in macrophages could ameliorate the disease severity and inflammatory response in colitis by regulating GBP5-NLRP3 axis, identifying a new therapeutic avenue for the treatment of colitis." (PMID 38903915, 2024). "However, in our study, we found in DSS-induced colitis, the mRNA levels and protein levels of HDAC3 were increased significantly." (PMID 38903915, 2024). "CX3CR1 positive macrophage are the resident monocytes and are significantly expanded in the acute phase inflammation in colitis, however, whether HDAC3 is involved in the process is unknown." (PMID 38903915, 2024). "F. prausnitzii intervention could decrease Th17 differentiation and attenuate colitis through inhibiting histone deacetylase 3 (HDAC3) and c-Myc-related metabolism in T cells." (PMID 38502145, 2024). "Inhibition of HDAC3 and conditional knockout of Hdac3 could protect mice from colon damage and inflammasome activation in colitis." (PMID 38903915, 2024). "Here, we found the expression of HDAC3 was upregulated in the macrophage of colitis model mice." (PMID 38903915, 2024). "To verify whether CX3CR1-positive monocytes HDAC3 is involved in the development of colitis, we conditionally knocked out HDAC3 in CX3CR1 positive monocytes (HDAC3 cKO) by crossing HDAC3f/f mice with CX3CR1cre mice." (PMID 38903915, 2024). "Therefore, the CX3CR1-positive monocytes HDAC3 may be a therapeutic target for colitis." (PMID 38903915, 2024). "In the current study, we found HDAC3 promoting IFN-γ induced expression of GBP5, which in turn, potentiated the activation of NLRP3 inflammasomes and aggravated the disease severity of DSS-induced colitis." (PMID 38903915, 2024). "CD4+ T cells from mice lacking epithelial HDAC3 induce severe colitis." (PMID 36602872, 2023).
endometriosis (10 papers, 2019 to 2025). The growth of functional endometrial tissue in anatomic sites outside the uterine body. "The loss of histone deacetylase 3 (HDAC3) is a result of failures in embryo implantation and decidualization and caused fibrosis in the endometrium, one of the symptoms of human endometriosis with reduced HDAC3 expression." (PMID 37270588, 2023). "Further mechanistic study linked loss of HDAC3 to loss of P4 signaling, revealing yet another P4 signaling regulator implicated in the P4 resistance of endometriosis." (PMID 31387263, 2019). "Additionally, while COL1A1 and COL1A2 are normally downregulated during decidualization, HDAC3 silencing induces their expression, suggesting that HDAC3 deficiency contributes to decidualization defects in endometriosis." (PMID 40072055, 2025). "HDAC3 shows reduced protein levels in the eutopic endometrium of infertile women with endometriosis compared to controls." (PMID 40072055, 2025). "A reduced expression of the HDAC3 enzyme has been demonstrated in the eutopic endometrium of infertile women with endometriosis compared to the control group." (PMID 35409163, 2022). "The decreased expression of deacetylase HDAC3 in eutopic endometrium in endometriosis patients directly affect the collagen gene expression." (PMID 33201593, 2021). "In DE lesions, it is possible that they may have HDAC3 inactivation which has been reported in eutopic endometrium from women with either endometriosis or adenomyosis and may lead to ERα mRNA instability, resulting in depressed ERα." (PMID 40521103, 2025). "Reduced protein levels of histone deacetylase 3 (HDAC3) in the ectopic endometrium of infertile women with endometriosis may impair fertility, as HDAC3 is crucial for endometrial receptivity and decidualization." (PMID 39345884, 2024). "Furthermore, the expression of HDAC3, one of HDACs that reduce gene expression, was significantly lower in the endometrium of patients with endometriosis." (PMID 37270588, 2023). "The hypothesis was that HDAC3 is a critical gene for endometrial receptivity in eutopic tissue of infertile women with endometriosis." (PMID 35409163, 2022). "However, this contrasts with findings in adenomyosis and endometriosis, probably due to the differential regulation of HDAC3 expression in different organs, or the limited number of HDAC3 studies in adenomyosis, which are currently only available from mouse models." (PMID 39595579, 2024). "HDAC1, HDAC2, HDAC3, Sirtuin 1, and Sirtuin 3, are the five most studied HDAC enzymes which seem to, at least partly, influence the pathophysiology of endometriosis." (PMID 37174627, 2023). "HDAC3 silencing in ESCs from women without endometriosis impairs in vitro decidualization, evidenced by decreased IGFBP1 and PRL expression." (PMID 40072055, 2025). "Expression of HDAC3, another epigenetic regulator, was also found decreased in endometrium from women with endometriosis as well as non-human primate and mouse models of endometriosis." (PMID 31387263, 2019).
heart failure (9 papers, 2013 to 2025). Inability of the heart to pump blood at an adequate rate to meet tissue metabolic requirements. "Overall, it has been shown that HDAC3 and NCoR1 are dysregulated in heart failure and is associated with adverse cardiac remodeling and dysfunction." (PMID 37674539, 2023). "The reduced expression level of HDAC3 was associated with better cardiac function in mice with heart failure." (PMID 34301918, 2021). "Accordingly, blockade of either CD47, HDAC3 or CaMKII has beneficial cardiac effects by reducing hypertrophy and softening heart failure thereby underlining a value of the TSP1/CD47 pathway in the pathogenesis of heart failure." (PMID 28714932, 2017). "In contrast, postnatal myocyte-specific KO of HDAC3 with myosin creatine kinase (MCK)-Cre only displayed lethal heart failure on HFD." (PMID 38983721, 2024). "Inhibition of HDAC3 and NCoR1 has been explored as a potential therapeutic strategy to mitigate cardiac remodeling and improve cardiac function in heart failure." (PMID 37674539, 2023). "Mechanically, HDAC3 inhibition prevented heart failure by inhibiting miR-18a-targeted adrenergic-receptor β3." (PMID 34301918, 2021). "HDAC3 in cardiomyocytes can induce cardiac dysfunction and heart failure." (PMID 34301918, 2021). "In addition, HDAC3 has been shown to promote heart failure and dietary death by exacerbating metabolic disturbances in mitochondria in the cardiomyocytes of mice fed with a high-fat diet." (PMID 34301918, 2021). "Similarly, another study found that HDAC3 KD, through intravenous injection of AAV-shRNA, attenuated heart failure induced by MI in mice." (PMID 38983721, 2024). "HDAC3 deacetylates DNA methyltransferase 1 (DNMT1) to inhibit ubiquitination-mediated degradation, which promotes the expression of DNMT1, which inhibits the expression of SHP-1 by methylation of the promoter region, thereby leading to heart failure induced by cardiomyocyte hypertrophy." (PMID 40710369, 2025).
Hyperglycemia (9 papers, 2012 to 2023). An increased concentration of glucose in the blood. "In this study, we found that hyperglycemia-induced epigenetic alterations in macrophages were likely mediated by HDAC3, which modifies macrophage metabolism and polarization, contributing to AS." (PMID 37215106, 2023). "Next, we determined the mechanism by which hyperglycaemia-induced HDAC3 upregulation aggravated MI/RI in diabetic rats." (PMID 33414413, 2021). "Although increased hepatic glucose production by HDAC3 has been shown to contribute to hyperglycemia seen in metabolic syndrome, given the repressive role of HDAC3 in lipogenesis, further study is necessary to evaluate the effect of HDAC3 in the different metabolic state of the body." (PMID 23363995, 2012). "Relative lower body weight, hyperglycemia, glucose intolerance, and dramatically increased sensitivity to STZ treatment in HDAC3 KO mice strongly suggest a developmental and/or functional defect in pancreatic islet β-cells." (PMID 27542279, 2016).
Anxiety (8 papers, 2018 to 2025). Intense feelings of nervousness, tension, or panic often arise in response to interpersonal stresses. "We found that HDAC3 inhibition reliably alleviated anxiety susceptibility to PTS + RS by remodelling microglial activation." (PMID 35251047, 2022). "Therefore, in phase summary, our findings reveal the HDAC3/Cox1/EP2 signalling axis in susceptibility to poststroke anxiety." (PMID 35251047, 2022). "Therefore, a causal link between HDAC3 expression disorder and anxiety-like symptoms has been established." (PMID 35251047, 2022). "In summary, we identified the role of the HDAC3/Cox1/EP2 signalling network in susceptibility to poststroke anxiety, and a protective approach of gamma visual stimulation might be a candidate strategy for alleviating susceptibility to additional stress exposure after cortex infarction." (PMID 35251047, 2022). "Activation of HDAC1, HDAC3, and NADPH oxidase 4 (NOX4) influences prostaglandin production in the cortex via microglia, which is associated with heightened anxiety and altered glutathione metabolism." (PMID 39851502, 2025). "Akt-mTOR signalling, one of the pathway phenotypes involved in the function of synapses by activating protein synthesis and alleviating depression or anxiety, is also enhanced upon HDAC3 inhibition." (PMID 35251047, 2022). "HDAC3 inhibition suppresses the inflammatory reaction and regulates the Cox1-EP2 network to influence anxiety susceptibility acquisition." (PMID 35251047, 2022). "Post-stroke anxiety is mediated by the up-regulation of histone deacetylase 3 (HDAC3) in activated microglia residing within the ischemic cortex, which facilitates the deacetylation process, subsequently leading to the nuclear translocation of p65 and activation of the NF-κB pathway." (PMID 39695746, 2024). "Therefore, we concluded that HDAC3 inhibition attenuates anxiety behaviour by restraining prostaglandin overproduction and downregulating neuronal EP2 expression in the amygdala." (PMID 35251047, 2022). "Further investigations on how HDAC3 is regulated or modified during anxiety-like behaviour and whether there are other messengers travelling through within-brain regions to affect neuron activity may accelerate the discovery for a long period." (PMID 35251047, 2022). "Lactate, a metabolite produced by exercise, induced resilience to social defeat stress and reversed social avoidance behavior and anxiety by modulating the activity of HDAC2 and HDAC3." (PMID 34065586, 2021). "Given that anxiety can affect performance in the cocaine CPP task, we tested the effects of HDAC3-Y298H-v5 in D1R-MSNs versus D2R-MSNs using the EPM." (PMID 33602824, 2021). "Importantly, it is worth noting that γ flicker stimulation has shown efficacy in inhibiting the activation of cortical microglia, down-regulating the HDAC3/COX1/EP2 signaling network, and alleviating anxiety-like behaviors in the photothrombotic stroke mouse model." (PMID 39695746, 2024).
cholangiocarcinoma (8 papers, 2017 to 2022). A carcinoma that arises from the intrahepatic biliary tree (intrahepatic cholangiocarcinoma) or from the junction, or adjacent to the junction, of the right and left hepatic ducts (hilar cholangiocarcinoma). "Previous findings showed that the overexpression of HDAC3 acts as an oncogenic feature and can promote the progression of cholangiocarcinoma and gastric cancer." (PMID 35715447, 2022). "Down-regulation or inhibition of HDAC3 reduces cholangiocarcinoma (CCA) cell growth and apoptosis." (PMID 30583572, 2018). "Down-regulation or pharmacological inhibition of HDAC3 by novel class I inhibitors, such as 4SC202, BG45, or SBHA, can inhibit cholangiocarcinoma (CCA) growth and promote apoptosis." (PMID 30583572, 2018). "Histone deacetylase 3 (HDAC3) regulates gene expression by removing acetyl groups from lysine residues, as well as has an oncogenic role in apoptosis and contributes to the proliferation of many cancer cells including cholangiocarcinoma (CCA)." (PMID 30866966, 2019). "However, the role of HDAC3 and the antitumor activity of its inhibitor MI192 are not known in cholangiocarcinoma (CCA)." (PMID 28569784, 2017).
rheumatoid arthritis (8 papers, 2018 to 2024). A chronic, systemic autoimmune disorder characterized by inflammation in the synovial membranes and articular surfaces. "Moreover, HDAC3 has also been reported to negatively regulate miR-19a-3p to increase interleukin 17 receptor A (IL17RA) expression in rheumatoid arthritis (RA)-associated interstitial lung disease (ILD)." (PMID 35626663, 2022).
Sepsis (8 papers, 2020 to 2025). Sepsis is defined as life-threatening organ dysfunction caused by a dysregulated host response to infection. "Histone deacetylase 3 deficiency alleviates sepsis-induced acute LI by maintaining mitochondrial quality control through the FOXO1–ROCK1 axis." (PMID 38671352, 2024). "Hence, we propose that Chr attenuates macrophage activation, reduces levels of intrapulmonary inflammation-associated cytokines, and improves LPS-induced sepsis shock through the HMGB1/NF-κB axis by regulating HDAC3." (PMID 33569375, 2020). "Because Chr significantly downregulated HDAC3 protein expression and inhibited NF-κB pathway activation in the sepsis shock mice model, we then performed in vitro model experiments to clarify the potential mechanisms involved." (PMID 33569375, 2020). "In addition, the expression of HDAC1 and HDAC3 was significantly reduced in CD16 + M1 macrophages from sepsis patients compared to that of normal individuals, particularly the HDAC1." (PMID 39294473, 2024). "Thus, the present study not only highlights the promising therapeutic potential of BRD3308 in sepsis-induced ALI but also emphasizes the regulatory role of HDAC3 in its pathogenesis." (PMID 39224841, 2024). "Notably, mice deficient in Hipk2 are more susceptible to cecal ligation and puncture (CLP)-induced sepsis, as HIPK2 can bind to and phosphorylate histone deacetylase 3 (HDAC3), inhibiting its enzymatic activity." (PMID 39234245, 2024). "In this study, we found that ALDH2 remarkably inhibited the cytoplasmic shuttle of HDAC3 induced by sepsis, and it might be related to the binding of the two proteins." (PMID 36992838, 2023). "This study is the first to demonstrate that ALDH2 may inhibit sepsis-induced translocation of HDAC3 from nucleus to mitochondria." (PMID 36992838, 2023). "This study provided a novel mechanism of myocardial pyroptosis through mitochondrial Histone deacetylase 3/HADHA- NOD-like receptor protein 3 inflammasome pathway and demonstrated a significant role of aldehyde dehydrogenase as a therapeutic target for myocardial pyroptosis in sepsis." (PMID 36992838, 2023).